SKAP2 (src kinase associated phosphoprotein 2)
Description:
May be involved in B-cell and macrophage adhesion processes. In B-cells, may act by coupling the B-cell receptor (BCR) to integrin activation. May play a role in src signaling pathway.
Synonyms: SKAP-HOM; PRAP; RA70; SAPS; SCAP2; SKAP55R
Tractability: Antibody: its Gene Ontology location is reachable by antibodies, with high confidence. PROTAC: ubiquitination databases record sites on it; its protein half-life has been measured.
Gene: Protein-coding gene on chromosome 7 (26,667,003 to 26,995,239, reverse strand). Ensembl gene ENSG00000005020.
Subcellular location: Cytoplasm
Subcellular location (Human Protein Atlas): Nucleoplasm; Cytosol
Pathways (Reactome):
Cell-Cell communication: Signal regulatory protein family interactions
Gene Ontology:
Molecular function: protein binding
Biological process: signal transduction
Cellular component: cytosol; nucleoplasm; plasma membrane; cytoplasm
Genetic constraint (gnomAD): Loss-of-function variants: 4 observed, 5.91 expected, observed/expected ratio (o/e) 0.68, 90% interval 0.33 to 1.51. That is too few expected variants to judge how well the gene tolerates losing a copy. Missense variants: 76 observed, 79.72 expected, observed/expected ratio (o/e) 0.95, 90% interval 0.79 to 1.15. Synonymous variants: 37 observed, 28.29 expected, observed/expected ratio (o/e) 1.31, 90% interval 1 to 1.71.
Homologues: Orthologues: chimpanzee SKAP2 (99% identical), macaque SKAP2 (98% identical), dog SKAP2 (94% identical), pig SKAP2 (92% identical), mouse Skap2 (90% identical), rabbit SKAP2 (90% identical), guinea pig SKAP2 (89% identical), rat Skap2 (81% identical), tropical clawed frog skap2 (58% identical), zebrafish skap2 (58% identical). Paralogues in human: SKAP1 (42% identical).
Diseases named in the same sentence as SKAP2 in open-access papers:
SKAP2 is named in the same sentence as 44 diseases in open-access papers, as found by Europe PMC text mining. Sharing a sentence is not in itself a finding about the gene and the disease. The quoted sentences say what the papers report.
type 1 diabetes (5 papers, 2017 to 2026). "Mutations in SKAP2 have been associated with several inflammatory disorders such as Type 1 Diabetes and Crohn’s disease." (PMID 37893161, 2023). "Genetic SKAP2 variants are associated with several inflammatory disorders, including type I diabetes, chronic venous disease, and Crohn’s disease." (PMID 37893161, 2023). "Moreover, a gain-of-function variant in SKAP2 resulted in enhanced activity of integrin pathways and migratory phenotype of macrophages, which likely contributed to type 1 diabetes development." (PMID 37224769, 2023). "Many genetic variants associated with increased type 1 diabetes (T1D) risk are located within the SKAP2 gene; however, the mechanisms by which these variants confer disease risk remain unclear." (PMID 41993266, 2026). "Among these genes, five (IL6R, RBPJ, SKAP2, SIRPG, UBASH3A) harbour a nearby type 1 diabetes-associated SNP." (PMID 37224769, 2023). "Genes SORCS1 and SKAP2 have relationship with diabetes type 1, diabetes mellitus type 2, cardiovascular diseases, and Edema." (PMID 28079101, 2017). "We found multiple genomic variants in GSTCD, SKAP2, SLC9B1 and BANK1 genes to be present at a relatively higher frequency in our patient cohort indicating a causal connection between these variants and the incidence of type 1 diabetes mellitus in Qatar." (PMID 34556755, 2021).
diabetes (4 papers, 2017 to 2026). "Furthermore, mutations or dysregulation of SKAP2 and WASP have been linked to autoimmune diseases such as diabetes." (PMID 37893161, 2023).
lung carcinoma (4 papers, 2017 to 2023). "Interestingly, expression of SKAP2 has been associated with a poorer prognosis in lung cancer and aberrant activity of SKAP2 has been observed in various cancer cell types." (PMID 37893161, 2023). "A subset of the 11 gene signature has recently been reported in the context of lung cancer, either as an oncogenic driver (e.g. CD79B) or a prognostic marker (e.g. TRAF3IP3, SKAP2, and SS18L2)." (PMID 33287695, 2020). "We identified seven proteins (Amph, Dok3, Ddx17, Mbip, Rim2, Skap2, TACC3, and Usp33) that are predicted to be EGFR interaction partners and/or share interaction partners within the EGFR pathway, and three of these (Amph, Rim2, and TACC3) show increased expression levels in lung cancer." (PMID 27956147, 2017).
autoimmune disorders (3 papers, 2020 to 2023). "Disruption of the interaction between SKAP2 and SIRPa has important implications for diseases such as cancer, autoimmune disorders, and inflammation." (PMID 37893161, 2023).
glioblastoma (2 papers, 2019 to 2024). The most malignant astrocytic tumor (WHO grade IV). "Src kinase-associated phosphoprotein 2 (SKAP2) is an adaptor protein for SFKs that interacts with WAVE2 and cortactin, antagonizing their adhesion-induced translocation to the membrane and inhibiting glioblastoma cell migration." (PMID 39354505, 2024). "Glioblastoma migration affected by WAVE2, SKAP2, cortactin, and FYN was also discussed earlier in relation to ABI1 and ABL1, linking EGFR and SFK signaling directly to ARP2/3-mediated actin polymerization." (PMID 39354505, 2024).
melanoma (2 papers, 2010 to 2024). A malignant, usually aggressive tumor composed of atypical, neoplastic melanocytes. "To this end, we selected 6 genes from the candidate list (ASPM, AKAP9, IMP3, PRKCA, RPA3, and SKAP2) based on literature support (see Discussion) to determine whether their knockdown would impact on the invasion of a human melanoma cell, 1205LU." (PMID 20520718, 2010).
Arthritis (1 paper, 2019). Inflammation of a joint. "The evidence provides insight into further understanding of the essential role of SKAP2 in inflammatory disorders, including arthritis." (PMID 31523167, 2019).
colitis (1 paper, 2024). Inflammation of the colon. "It was observed that deficiency of SKAP2 in mice with colitis resulted in increased LPS-induced inflammation and tumorigenesis." (PMID 38482001, 2024). "Deletion of SKAP2 in colitis-induced mouse models demonstrated activation of the NF-κB pathway along with upregulation of cytokines such as TNF-α, CXCLs, and interleukins." (PMID 38482001, 2024).
experimental autoimmune encephalomyelitis (1 paper, 2017). An autoimmune demyelinating disease of the central nervous system that is produced experimentally in animals by the injection of homogenized brain or spinal cord in Freund's adjuvant. "Skap2- and Sirpα-deficient mice are resistant to experimental autoimmune encephalomyelitis and collagen-induced arthritis, two models for the human diseases multiple sclerosis and rheumatoid arthritis that have integrin-dependent components." (PMID 28374850, 2017).
gastric cancer (1 paper, 2019). A primary or metastatic malignant neoplasm involving the stomach. "Additionally, SKAP2 was detected in stromal cells infiltrating human gastric cancer tissues, and promoted tumor-associated macrophage infiltration and facilitated metastatic progression." (PMID 31523167, 2019).
Infertility (1 paper, 2025). "Mechanistically, we establish a direct link between infertility-associated Hnrnpr mutations and aberrant Skap2 splicing, revealing a previously unrecognized regulatory axis crucial for late spermatogenic progression." (PMID 41436426, 2025).
male infertility (1 paper, 2025). The inability of the male to effect fertilization of an ovum after a specified period of unprotected intercourse. "Moreover, increased DNA fragmentation and complete failure of fertilization were observed in D-cKO mice, demonstrating that germline-specific deletion of Skap2 leads to loss of genetic integrity and male infertility." (PMID 41436426, 2025). "Collectively, these findings not only uncover a novel mechanism whereby m6A-mediated splicing coordinates sperm differentiation, but also develop extracellular vesicles SKAP2-based intervention as a potential therapeutic strategy for male infertility." (PMID 41436426, 2025). "Altogether, these findings identify hnRNPR as a pivotal regulator of m6A-mediated Skap2 splicing during spermiogenesis and highlight extracellular vesicle SKAP2 as a promising therapeutic target for poor sperm quality and male infertility." (PMID 41436426, 2025). "To estimate the therapeutic effect of mEVs-SKAP2 on male infertility, we carried on mEVs-SKAP2 trial on human semen samples derived from three groups: normal population, individuals harboring HNRNPR mutations and patients diagnosed with idiopathic asthenoteratozoospermia." (PMID 41436426, 2025). "Collectively, these findings highlight SKAP2 as a promising nonhormonal therapeutic target for correcting cytoskeletal defects in late-stage sperm development and suggest that EV-based protein delivery may represent a novel strategy for treating certain forms of male infertility." (PMID 41436426, 2025).
neutropenia (1 paper, 2020). A decrease in the number of neutrophils found in the blood. "The growth of a ΔyopH mutant was partially restored in Skap2-deficient (Skap2KO) mice compared to wild-type (WT) mice, while induction of neutropenia further enhanced the growth of the ΔyopH mutant in both WT and Skap2KO mice." (PMID 32392230, 2020).
Obesity (1 paper, 2020). Accumulation of substantial excess body fat. "Still, whether through the regulation of BMSCs differentiation (FMN1 and BMPR1B), glucose metabolism (MAGI2), or initiation of the inflammatory process (SKAP2), these genes could be relevant to the development of obesity." (PMID 33003475, 2020).
preeclampsia (1 paper, 2023). Preeclampsia is a hypertensive disorder of pregnancy that is characterized by new-onset hypertension with proteinuria presenting after 20 weeks of gestation, and depending on mild or severe forms may initially present with severe headache, visual disturbances, and hyperreflexia. "SKAP2 was downregulated in the villous tissues of patients with failed pregnancies, while MXD1 was associated with early and late gestation in patients with severe preeclampsia." (PMID 36833425, 2023).
tobacco-use disorder (1 paper, 2017). "Gene-disease association shows SORCS1, SKAP2, and CELSR2 genes are related with genetic susceptibility, and genes SORCS1 and PCDH10 are related with tobacco-use disorder." (PMID 28079101, 2017).
tumor (14 papers, 2008 to 2024). "Our CGH array disclosed a duplication in 7p15.2, both in the PB and tumor sample, which contains part of a gene, SKAP2, whose increased copy number is associated with the development of a different type of cancer." (PMID 39408992, 2024). "Lastly, the PI3K/Akt pathway, which has previously been linked to SKAP2, has been found to affect tumour cell invasiveness." (PMID 37893161, 2023). "An interesting study revealed the role of SKAP2 on macrophage podosome formation for the promotion of tumor invasion and metastasis." (PMID 38482001, 2024). "Furthermore, when SKAP2 null macrophages were injected, the macrophage tumor infiltration and growth were reduced." (PMID 38482001, 2024). "SKAP2 is an adaptor protein that plays an important role in src signaling and is involved in a wide range of intracellular processes, such as suppression of cell migration and tumor invasion by inhibition of actin polymerization." (PMID 28241754, 2017). "The duplication of region 7p15.2 is present both on the peripheral blood (PB) and tumor sample but absent in the parents; the duplication involves exons 1–4 of the SKAP2 gene and is not included among the known copy number variations (CNVs)." (PMID 39408992, 2024). "Additionally, fifteen genes were associated with cancer control; among these, three were related to immunity (MAGT1, RFXANK and SKAP2), two (ADGRL3 and TENM3) were related to cell adhesion, and two (ADAM11 and TEP1) were found to be tumor suppressor genes." (PMID 34107880, 2021). "Transcriptional profiling classified the Ta tumours as luminal (high expression of luminal markers such as GATA3, PPARG, FOXA1 and XBP1 as well as differentiation markers such as UPK1A and KRT20) as well as non-aggressive (high expression of SKAP2, FABP4, MBNL2 and ID1)." (PMID 28916750, 2017).
cancer (10 papers, 2007 to 2024). A tumor composed of atypical neoplastic, often pleomorphic cells that invade other tissues. "SKAP2 encodes src kinase associated phosphoprotein 2 and participates in different physiological processes, including integrin signaling, cell migration and cancer progression." (PMID 31523167, 2019). "From COSMIC cancer database, we extracted seven non-synonymous mutations detected repeatedly in SKAP2 gene." (PMID 29568343, 2018). "SKAP2 has been found to be tyrosine phosphorylated in macrophages when co-cultured with cancer cells." (PMID 37893161, 2023). "The effect of SKAP2 on this phenomena has not yet been clarified, but inhibition of FAK, Src, and PI3K (which are all known to stimulate Akt activation) have all lead to inhibiting pressure-induced adhesion of various cancer cells." (PMID 37893161, 2023).
infection (6 papers, 2020 to 2023). The state of being infected such as from the introduction of a foreign agent such as serum, vaccine, antigenic substance or organism. "SKAP2 is essential for integrin-stimulated ROS production in neutrophils, is dephosphorylated in neutrophils injected with YopH during tissue infection, and associates with YopH in macrophages." (PMID 32392230, 2020). "WT and Skap2-/- mice were infected with 5 × 103 cfu and were monitored for weight loss, bacterial colonization, and innate cell recruitment at 8, 16, and 24 hr post infection (hpi)." (PMID 32352382, 2020). "Our experiments reveal that SKAP2 plays a key role in host defense in the hematopoietic compartment against K. pneumoniae 43816 in pulmonary infections in a murine lung model of infection." (PMID 32352382, 2020). "It would be interesting to explore if the SKAP2-mediated K. pneumoniae-stimulated responses occur in human neutrophils, and whether neutrophils (or other cell types) from individuals carrying specific Skap2 variants respond differently K. pneumoniae 43816 infection." (PMID 32352382, 2020). "In conclusion, SKAP2-dependent signaling in neutrophils is essential for K. pneumoniae-activated ROS production and for promoting bacterial clearance during infection." (PMID 32352382, 2020). "We show that a previously identified target of YopH, SKAP2, controls some of the pathways essential for YopH to inactivate during infection." (PMID 32392230, 2020). "Using a murine model of K. pneumoniae 43816 infection, we characterized the role of SKAP2 in pulmonary host defense against K. pneumoniae in this study." (PMID 32352382, 2020). "During tissue infection, other SKAP2-independent pathways may be triggered to generate ROS, which YopH can block, thus a ΔyopH mutant is susceptible to the ROS produced." (PMID 32392230, 2020). "Understanding the role of SKAP2 in fighting infections may help scientists better understand the immune system." (PMID 32352382, 2020). "As Skap2-/- neutrophils are present in infected tissues, the uncontrolled K. pneumoniae growth may occur because of defects in the antimicrobial functions of Skap2-/- neutrophils at the site of infection." (PMID 32352382, 2020). "By exploring the interplay between Yptb effector YopH and the neutrophil adaptor protein, SKAP2, during tissue infection, we demonstrate the role YopH plays in protecting Yptb from neutrophil-mediated ROS production as well as the role SKAP2 plays in mediating neutrophil antimicrobial functions." (PMID 32392230, 2020). "Thus, YopH appears to play a major role in protecting Yptb from ROS production during tissue infection, in part through its ability to block SKAP2-controlled pathways, while YopE may play a more prominent role at the phagocytic cup in inactivating Rac1 and RhoG rather than in inactivating Rac2." (PMID 32392230, 2020). "Together, these data indicate that neutrophils cannot control K. pneumoniae 43816 infection in the absence of SKAP2 in the hematopoietic compartment." (PMID 32352382, 2020). "Combined, these results indicate that the K. pneumoniae 43816 strain is resistant to neutrophil phagocytosis regardless of SKAP2 expression, but can elicit SKAP2-independent degranulation during infection." (PMID 32352382, 2020). "While SKAP2 is necessary for limiting colonization of ΔyopH mutant, it does not appear to limit neutrophil migration to spleens in our infection models." (PMID 32392230, 2020). "(E–F) WT and Skap2-/- mice were injected intraperitoneally with 50 μg of α-Ly6G (1A8) or 20 μg of α-CCR2 (MC-21) to deplete neutrophils and iMOs, respectively, or PBS 16 hr prior to infection." (PMID 32352382, 2020). "Finally, SKAP2 was important for ROS production after infection with another gram-negative bacterial strain, a type 3 deficient Y. pseudotuberculosis strain, ΔyscF." (PMID 32352382, 2020).
infection (continued). "While FcγR is unlikely to be activated by Yptb during infection of a naïve host, this result nonetheless raises the possibility that neutrophils have other receptors that may recognize Yptb, signal and function independently of SKAP2, leading to ROS generation in the absence of YopH." (PMID 32392230, 2020).
immune disease (2 papers, 2022 to 2025). "Among those, six gene knockouts resulted in an immune disease, including Cd28, Ndfip1, Skap2, Tmem258, Tnfrsf1a, and Tnfrsf9." (PMID 35591976, 2022). "However, increased expression of FCRL3, SKAP2, and AP003774 was associated with lower risk of T1D and RA, while decreased expression of BACH2 and RPS26 increased immune disease risk." (PMID 41361473, 2025).
SKAP2 also shares sentences with these, for which no sentence is quoted: type 2 diabetes (3 papers); atherosclerosis (2); chronic heart failure (2); pancreatic cancer (2); abscesses (1); Alzheimer disease (1); Ataxia (1); Autoimmunity (1); bladder carcinoma (1); cardiovascular diseases (1); chronic osteomyelitis (1); Crohn disease (1); esophageal cancer (1); fungi infection (1); Hyperammonemia (1); inflammatory bowel disease (1); kidney damage (1); mental disorder (1); multiple sclerosis (1); non-small cell lung carcinoma (1); pancreatic duct adenocarcinoma (1); rheumatoid arthritis (1); schizophrenia (1); Sepsis (1).